SIRT1 (sirtuin 1)
Diseases named in the same sentence as SIRT1 in open-access papers (continued):
Sharing a sentence is not in itself a finding about the gene and the disease.
cancer (continued). "Future research will further explore the specific mechanisms of action of SIRT1 modulators in different types of cancer, providing a scientific basis for the development of more effective cancer therapies." (PMID 40109363, 2025). "Among all SIRTs, SIRT1 has been extensively researched for its dual role in cancer, contributing to tumour suppression and promotion." (PMID 40136715, 2025). "Subgroup analyses revealed that ethnic origin has an impact on the role of SIRT1 expression and the clinicopathological features of cancer." (PMID 39858444, 2025). "By activating or repressing key transcription factors such as PGC-1α and FOXO, Sirtuin 1 (SIRT1) orchestrates metabolic reprogramming in cancer cells to adapt to fluctuations in energy availability." (PMID 41278473, 2025). "Their functions in cancer are dualistic: certain SIRTs (e.g., SIRT1) can promote tumor progression in some cancers, while others (e.g., SIRT6) act as tumor suppressors by maintaining genomic stability." (PMID 41213956, 2025). "SIRT1 is a histone deacetylase that influences DNA repair, mitochondrial function, inflammatory pathways, and gene expression related to aging and cancer, potentially delaying the onset of age-related diseases including CRC." (PMID 39090501, 2025). "SIRT1 inhibition promotes apoptosis, enhances sensitivity to chemotherapy, and reduces chemoresistance in various cancers." (PMID 41008982, 2025). "On the one hand, SIRT1 protects organisms against cancer by maintaining genomic integrity and DNA repair." (PMID 39858444, 2025). "In fact, this polyphenol upregulates SIRT1, a key regulator in apoptosis and cellular senescence, across various cancer types, enhancing cancer cell sensitivity to chemotherapy and inducing apoptosis." (PMID 40663150, 2025). "SIRT1 is believed to be a factor in tumorigenesis and has been observed to be highly expressed in a variety of cancers, including prostate cancer and acute myeloid leukemia." (PMID 40421455, 2025). "Large-scale clinical trials are required to confirm the efficacy and safety of SIRT1 inhibitors in different cancer types." (PMID 41008982, 2025). "In cancer, SIRT1 possesses a dichotomous role by regulating the expression and function of a wide array of proteins at different phases of cancer development." (PMID 39215785, 2025). "By modulating the activity of these factors in a redox-dependent manner, SIRT1 enables cancer cells to sustain growth and resist metabolic and oxidative stress." (PMID 41008982, 2025). "SIRT1 (discussed in “E2F1-dependent apoptosis in cancer therapy”) has been demonstrated to promote cancer chemoresistance." (PMID 40517236, 2025). "In lab studies, blocking SIRT1 with experimental drugs has been shown to make cancer cells more sensitive to chemotherapy and reduce their ability to survive." (PMID 41300302, 2025). "By coordinating these cellular responses, SIRT1 functions as a guardian against tumorigenesis, aligning its anti-cancer effects with the metabolic adaptations induced by CR." (PMID 39940361, 2025). "Previous studies have indicated that SIRT1 exhibits a dual role in cancer biology, acting as either a tumor suppressor or a tumor promoter, depending on the specific tumor-specific carcinogenic pathways." (PMID 41281762, 2025).
cancer (continued). "In GC, SIRT1 similarly promotes tumor progression via autophagy and chemoresistance, but studies also highlight its potential anti-cancer effects through ferroptosis regulation." (PMID 40567502, 2025). "Depending on the cancer type and stage, SIRT1 can either slow down cancer growth or help it spread and resist treatment." (PMID 41300302, 2025). "By demonstrating that SIRT1‐mediated deacetylation of histone H3 promotes PD‐L1 nuclear localization, we uncovered a novel mechanism by which cancer cells evade immune surveillance." (PMID 39988985, 2025). "The objective of this review was to provide an integrated framework linking SIRT1-mediated deacetylation to redox regulation and senescence control in cancer." (PMID 41008982, 2025). "Despite promising preclinical evidence, clinical trials assessing the efficacy of SIRT1 inhibitors in cancer therapy are limited, possibly due to contradictory findings regarding SIRT1’s role as an oncogene or tumor suppressor." (PMID 40517236, 2025). "MSCs overexpressing SIRT1 significantly expedited cancer initiation and progression by secreting CCL5, which enhanced macrophage recruitment and amplified the inflammatory response." (PMID 40676710, 2025). "Sirt1 expression, which promotes cell survival and inhibits apoptosis in cancer cells, decreased in a dose-dependent manner as the Oxamate concentration increased." (PMID 40565174, 2025). "They found that the high expression of SIRT1 was statistically significantly correlated with the proliferation status of GC, advanced cancer stage, poor overall survival (OS), recurrence free survival, and increased number of metastatic lymph nodes." (PMID 40567502, 2025). "Because its actions can either promote or hinder cancer formation depending on the particular cellular milieu, signaling pathways, or disease targets involved, SIRT1 plays a dual function in cancer." (PMID 40708783, 2025). "Chronic inflammation is a major contributor to tumorigenesis, and by inhibiting NF-κB, SIRT1 reduces the pro-inflammatory conditions that can drive cancer development." (PMID 39940361, 2025). "By modulating mitochondrial dynamics and autophagy, SIRT1 helps cancer cells maintain energy homeostasis, facilitating their growth and survival." (PMID 41300302, 2025). "While SIRT1 can promote cancer progression by enhancing c-MYC activity, DBC1 counteracts this process, thereby exhibiting anticancer effects." (PMID 40692869, 2025). "Through these enzymatic activities, SIRT1 regulates numerous cellular processes, including aging, metabolism, stress responses, and cancer." (PMID 41300302, 2025). "This review integrates the mechanistic perspectives on how SIRT1-mediated deacetylation enables cancer cells to maintain redox homeostasis and evade senescence." (PMID 41008982, 2025). "The interaction of SIRT1 with immunomodulatory compounds in most forms of cancer ensures it is a target for immuno-metabolic therapy approaches." (PMID 41425553, 2025). "Cancer cells exploit this adaptive mechanism by upregulating the NAD+–SIRT1 axis to reinforce antioxidant defenses, resist oxidative damage, and evade senescence." (PMID 41008982, 2025). "Through the deacetylation of transcription factors like FOXO1 and NF-κB, SIRT1 suppresses the expression of pro-inflammatory cytokines and antigen-presenting machinery, thereby promoting immune evasion in cancer." (PMID 41008982, 2025).
cancer (continued). "It has been suggested that targeting the autophagy pathway, including its regulators like SIRT1 and miRNAs, presents a promising strategy to overcome therapy resistance and improve cancer treatment outcomes." (PMID 40650051, 2025). "Resveratrol demonstrates multi-faceted anti-cancer properties through its modulation of SIRT1 and HDACs." (PMID 40663150, 2025). "SIRT1 plays a significant role in the progression and treatment resistance of various cancers, including breast and gynecological malignancies." (PMID 41300302, 2025). "This activation is particularly important in the context of cancer suppression, as SIRT1 modulates critical pathways involved in cell survival, proliferation, and stress resistance." (PMID 39940361, 2025). "Further investigation is warranted to establish the link between SIRT1 and cancer progression, facilitating the development of novel strategies for early detection and targeted treatment of gastrointestinal cancers." (PMID 41020376, 2025). "Second, SIRT1 plays dual roles in cancer, acting as a tumor suppressor in certain contexts (e.g., early-stage cancers or low stress environments) and as a tumor promoter in other contexts (e.g., advanced or redox-stressed tumors)." (PMID 41008982, 2025). "SIRT1 and SIRT2 have emerged as promising targets for therapeutic interventions in various diseases associated with gut dysbiosis, including cancer, neurodegenerative disorders, and metabolic conditions." (PMID 40136715, 2025). "The anti-cancer effects of caloric restriction (CR) in mammals have been well-documented, with SIRT1 playing a significant role in energy metabolism." (PMID 40567502, 2025). "SIRT1 is a transcriptional co-activator broadly involved in physiological processes, including cancer, oxidative stress, aging, metabolism, apoptosis, proliferation, and inflammation, largely through regulation of PGC-1α deacetylation." (PMID 40661259, 2025). "In cells other than cancer cells, SIRT1 activation has beneficial effects on cardiovascular and hepatic cells, thereby extending life expectancy." (PMID 39940750, 2025). "This includes investigating the role of SIRT1 in different stages of cancer development and identifying biomarkers that can predict SIRT1’s function in individual patients." (PMID 40567502, 2025). "Preclinical studies show that pharmacological inhibition of SIRT1 (e.g., with EX-527 or cambinol) restores chemosensitivity and reduces tumor cell viability, suggesting potential for SIRT1 inhibitors as adjuncts in cancer therapy." (PMID 41300302, 2025). "Acetylation at K382 enhances proapoptotic transcriptional activity, whereas SIRT1-mediated deacetylation suppresses this function, thereby protecting cancer cells from ROS-induced apoptosis." (PMID 41008982, 2025). "Pharmacological inhibition of SIRT1 with EX-527 also demonstrated anti-cancer effects, reducing cell proliferation and metastasis." (PMID 41471349, 2025). "Accordingly, therapeutic strategies targeting the SIRT1–redox–senescence axis represent promising approaches for cancer treatment." (PMID 41008982, 2025). "Specifically, SIRT6 induces MDM2-mediated degradation of SIRT1, thereby relieving the protective role of SIRT1 and allowing accumulation of reactive oxygen species (ROS), which ultimately drive cancer cell death." (PMID 41463311, 2025). "Future research into SIRT1 inhibitors has substantial potential for the development of more targeted and effective cancer therapies." (PMID 41008982, 2025). "Future research should aim to elucidate the cancer type-specific functions and redox sensitivities of SIRT1, develop predictive biomarkers, and optimize therapeutic targeting to enhance clinical applicability." (PMID 41008982, 2025).
cancer (continued). "Its role in cancer occurrence, progression, or survival remains controversial, as SIRT1 has been reported to exert both oncogenic and tumor-suppressive effects." (PMID 40507674, 2025). "Future efforts should emphasize strategies that selectively target SIRT1 in cancer cells while sparing their normal counterparts, thereby improving therapeutic specificity and reducing off-target effects." (PMID 41008982, 2025). "Initially studied in age‐related diseases, neurodegeneration, inflammatory disorders, myopathies, and diverse cancers, SIRT1 is established as a key regulatory factor and therapeutic target in GBM multiforme pathogenesis." (PMID 41208649, 2025). "One possible explanation for the limited efficacy of resveratrol in cancer therapy is that resveratrol activates SIRT1." (PMID 40517236, 2025). "In cancer, SIRT1 can influence tumorigenesis by modulating cell survival pathways and inhibiting tumor suppressor proteins." (PMID 40330466, 2025). "While SIRT1 typically suppresses senescence, it can promote tumorigenesis in cancers by enabling tumor cells to evade apoptosis." (PMID 40052151, 2025). "By deacetylating FOXO, SIRT1 enhances cellular defenses against ROS, helping maintain genomic integrity and prevent cancer development." (PMID 39940361, 2025). "SIRT1-mediated ferroptosis is increasingly recognized as a pivotal factor in diverse cancer treatment strategies." (PMID 40109363, 2025). "SIRT1 has been shown to play a complex and often contradictory role in cancer development and progression." (PMID 40664665, 2025). "MHY2245 is a synthetic inhibitor of SIRT1 that triggers both autophagy and apoptosis in cancer cells." (PMID 41300302, 2025). "SIRT1 also suppresses inflammatory pathways, such as the NF-κB signaling pathway, which is often upregulated in cancer." (PMID 39940361, 2025). "Further research has shown that liver proliferation and cancer progression are driven by the downregulation of SIRT1 and its downstream effector, PGC-1α, which is suppressed by the CCAAT/enhancer binding protein β-histone deacetylase 1 complex." (PMID 40052151, 2025). "Epithelial–Mesenchymal Transition (EMT) and Metastasis: SIRT1 has been implicated in promoting EMT in TNBC, a key process in cancer metastasis." (PMID 41300302, 2025). "SIRT1 was shown to bind and promote FoxO1 to translocate into the nucleus, enhancing the transcription of target genes involved in cancer development (Bosch-Presegué and Vaquero, 2011)." (PMID 40421455, 2025). "SIRT1 also deacetylates c-Myc and further negatively regulates the transcription of tumor suppressor-related genes to promote the development of cancer." (PMID 40421455, 2025). "Conversely, CAF-derived exosomal DACT3-AS1 enhances oxaliplatin sensitivity in cancer cells through sirtuins 1 (SIRT1)-mediated ferroptosis." (PMID 40285867, 2025). "In cancer cells, SIRT1 activation enhances genomic stability by promoting DNA repair mechanisms, reduces oxidative stress by improving mitochondrial function, and induces apoptosis in damaged or pre-cancerous cells." (PMID 39940361, 2025). "Targeting SIRT1 offers a promising strategy to improve cancer treatment outcomes, particularly in chemoresistant subtypes." (PMID 41300302, 2025). "Future research should prioritize the development of cancer-selective SIRT1 inhibitors, the integration of biomarker-driven clinical trial designs, and exploration of rational combination strategies with chemotherapy, immunotherapy, or metabolic modulators." (PMID 41008982, 2025).
cancer (continued). "Reconstitution of SIRT1 expression triggered apoptosis and autophagy, further confirming its anti-cancer action in this case." (PMID 41425553, 2025). "For example, in malignant tumors such as colorectal cancer, pancreatic cancer, prostate cancer, and skin cancer, SIRT1 primarily exerts tumor-suppressing effects." (PMID 41281762, 2025). "SIRT1, an NAD+-dependent deacetylase, plays diverse roles in physiological processes and has been implicated in cancer development." (PMID 40567502, 2025). "At the pan-cancer level, SIRT1 analysis revealed that SIRT1 has a bivalent function, involved in DNA repair, inflammation, and immune infiltration." (PMID 41425553, 2025). "SIRT1 plays a role in the development, propagation, and advancement of multiple malignant tumors, such as lung, breast, prostate, leukemia, colon, melanoma, ovarian, and gastric cancers." (PMID 41304967, 2025). "Further research has demonstrated that metformin can promote cancer cell pyroptosis through activation of the SIRT1/NF-κB signaling pathway." (PMID 40149884, 2025). "To date, there is evidence that all seven isoforms contribute to cancer development, while SIRT1-3 and 6 contribute to metabolic and neurodegenerative diseases." (PMID 41304967, 2025). "Collectively, SIRT1-mediated deacetylation of FOXO1 represents a crucial mechanism by which cancer cells evade senescence and apoptosis, while maintaining redox homeostasis." (PMID 41008982, 2025). "On the other hand, in some types of cancer cells, Sirtuin 1 activation is able to inhibit glucose uptake." (PMID 40308696, 2025). "When NAD+ levels are maintained or elevated, SIRT1 activity is enhanced, which inhibits senescence-related pathways and promotes cancer cell proliferation and survival." (PMID 41008982, 2025). "Initially, through TCGA database analysis, we assessed the pan-cancer expression of SIRT1 and observed its low expression across various tumors such as BLCA, BRCA, CESC, KICH, KIRP, COAD and READ (." (PMID 40229278, 2025). "By clearing dysfunctional mitochondria, SIRT1 supports cancer cell survival in the face of oxidative stress and metabolic challenges." (PMID 41300302, 2025). "NAMPT and SIRT1 are overexpressed in several malignant tumor types, including colorectal, ovarian, breast, gastric, thyroid, and prostate cancers, as well as numerous malignant lymphomas, due to the increased requirement for energy metabolism." (PMID 40085284, 2025). "SIRT1 promotes cancer cell survival and adaptation under stressful conditions by deacetylating various transcription factors and metabolic regulators." (PMID 41008982, 2025). "By improving mitochondrial efficiency and reducing ROS production, SIRT1 contributes to a healthier cellular environment, which is crucial for limiting cancer cell proliferation." (PMID 39940361, 2025). "SIRT1, the most extensively studied sirtuin, has multidimensional regulatory functions in cancer biology." (PMID 40754534, 2025). "Through these molecular mechanisms, SIRT1 enables cancer cells to adapt to oxidative stress, evade apoptosis and senescence, and escape immune surveillance." (PMID 41008982, 2025). "For instance, SIRT1 has been shown to promote cancer progression by deacetylating and activating oncogenic transcription factors, while SIRT5 has been implicated in tumor suppression by regulating mitochondrial metabolism." (PMID 40710366, 2025). "Overall, these findings show that there are many ways NK cell activity is reduced in cancer, influenced by epigenetic enzymes like SIRTs (SIRT1, SIRT2, SIRT6), surface regulators like CD38, and signaling pathways like TGFβ-SMAD4." (PMID 41425553, 2025).